IL9 (interleukin 9)
Diseases named in the same sentence as IL9 in open-access papers (continued):
Sharing a sentence is not in itself a finding about the gene and the disease.
infection (continued). "The results suggest that IL-9 can potentially influence IL-17 and IFN-γ responses in Cm infection." (PMID 25646821, 2015). "IL-9 deficiency, using 129×C57Bl/6 (F2) Il9−/− mice backcrossed six times onto a BALB/c background, led to modest reductions in mast cell numbers but did not alter the outcome of infection with the flagellated intestinal protozoan parasite Giardia lamblia." (PMID 24586147, 2014). "Infection of these mice with T. muris augmented worm burden and reduced IL-9 but not IL-13 production in mesenteric lymph nodes." (PMID 24586147, 2014). "We observed both IL-9 producing CD4+ and CD4− cells during infection at very low frequencies." (PMID 24516385, 2014). "Interestingly, IL-9 and IL-17a were found in higher concentrations following infection with all three viruses, irrespective of the mouse strain." (PMID 39466030, 2024). "Pro-inflammatory (IFNγ, IL-6, TNFα), Treg (IL-10, TGFβ1, TGFβ3), Th9 (IL-9), Th17 (IL-17), and Th2 (IL-4, IL-13) cytokines, total IgM and IgG, as well as gene expressions of FoxP3, STAT5+, IFNγ-R1, and ROR alpha+, were measured at day 1, day 7, day 14, day 21, and day 28 post-infection." (PMID 37569646, 2023). "Hence, the presence of the ST2- IL-9+ ILC2 population in the small intestine described here might be explained by this regulatory loop, where IL-33 and IL-25 are induced upon infection, promoting iILC2s that lack ST2 and express effector cytokines in vivo." (PMID 35711429, 2022). "Levels of six other chemokines and cytokines (IL-5, IL-1α, IL-3, G-CSF, IL-9, and eotaxin) were modestly increased or not increased with infection over time, but were reduced in basoIL-18R (−) mice relative to basoIL-18R (+) mice at 4 d PI (IL-5) or at 10 d PI (IL-1α, IL-3, G-CSF, IL-9, eotaxin)." (PMID 35985797, 2022). "Others, such as IL-1α, IL-2, IL-7, IL-9, IL-10, IL-12p40, IL-13, and VEGF were present at equivalent concentrations in lungs of infected and control mice during the first 5 days, but at significantly reduced concentrations in lungs of infected mice at day 7 post-infection." (PMID 35812400, 2022). "However, the early mast cell degranulation that facilitates intestinal parasite control during the first week of infection is independent of adaptive immunity and promoted by IL-9." (PMID 33351862, 2020). "Moreover, for in vivo study, goats were infected with different doses (P-800, P-2400, and P-8000) of H. contortus infective larva (L3) and immunomodulatory effects on Th9 cells, IL-9 immune response and TGF-β/Smad signaling regulator were evaluated at 7, 10, 14, 18, 21, 28 Days Post Infection (DPI)." (PMID 32243446, 2020). "Furthermore, the levels of interleukin (IL)-2, IL-4, IL-6, IL-22, and interferon (IFN)-γ, but not that of tumor necrosis factor alpha (TNF-α), IL-10, and IL-9, increased to their highest levels at day 4 post-infection and decreased thereafter." (PMID 31711531, 2019). "In contrast, no significant upregulation of IL-9 protein was evidenced following MR766 infection." (PMID 29967565, 2018). "In addition to classical Th9 cells responding to antigen-stimulation, we also observed increased frequencies of Th2 cells expressing IL-9 (IL-4/IL-9 co-expressing), indicating that other CD4+ T cell subsets also respond to Ss infection with the capacity to produce more IL-9." (PMID 26730582, 2016). "Whether the source of IL-9 ultimately matters in the context of resistance to infection is still not clear." (PMID 26730582, 2016). "Surprisingly, although significant IL-9 response was induced by Cm lung infection, the blockade of this cytokine in vivo failed to change either T cell or B cell responses and had no significant impact on infection process." (PMID 25646821, 2015). "Interestingly, 4 proteins (IFNγ, IL9, IP10, and MIP1α) overlapped between the two identified signatures, suggesting differential expression of these is associated with active TB disease, rather than infection per se." (PMID 35401549, 2022).
infection (continued). "IL-9 signalling by TFH cells has also been shown to be playing a role in memory B cell differentiation out of the GC, however, it is not yet clear whether IL-9-mediated induction of memory B-cell fate is a generalizable feature across different infection models." (PMID 36845573, 2021). "For the cytokines Rantes, GM-CSF, Eotaxin, IL-13, IL-9, IL-6 and IL-1b there was no significant mean difference in concentration among the first three time-points (15 min, 30 min and 60 min) and the last two time-points (4 hrs and 10 hrs) for both the H37Rv and Δ-mce1 H37Rv-infections." (PMID 22039457, 2011). "None of the increases in IL-4, IL-5, IL-9, and IL-13 in response to SEA were correlated with pretreatment infection intensity." (PMID 24357629, 2014). "Treg and BTLA+ T cells expand during infection and either Treg depletion or absence of BTLA or its ligand, Herpes Virus Entry Mediator (HVEM), results in elevated IL-9 production, accelerated mast cell activation and rapid expulsion of S. ratti from the intestine." (PMID 33351862, 2020).
cancer (79 papers, 2010 to 2025). A tumor composed of atypical neoplastic, often pleomorphic cells that invade other tissues. "Largely experimental studies suggest that IL-9 is positively associated with limiting cancer outgrowth." (PMID 39439893, 2024). "Il-9 role as a diagnostic and prognostic marker varies across different cancers." (PMID 39334861, 2024). "The underlying mechanism by which IL-9 inhibits cancer growth is to be further investigated." (PMID 28002799, 2017). "In the TME, Th1, and Th9 subsets of CD4+T-cells enhance CD8+T-cell antitumor activity through cytokines like IL-2, IFN-γ, and IL-9, correlating with improved outcomes across cancers." (PMID 40260236, 2025). "The authors demonstrated that recombinant IL-9 (rIL-9) enhanced the anti-cancer activity of anti-PD-1 treatment (pembrolizumab) ex vivo by inducing a cytotoxic response in CD8 TILs." (PMID 37189417, 2023). "Recent translational investigations suggest that the anticancer activity of IL-9 also extends to some human cancers." (PMID 37189417, 2023). "Collectively, these results demonstrated that recombinant IL9 treatment delayed the growth of cancers and enhanced survival when cancer cells were implanted with macrophages." (PMID 36968220, 2023). "Nevertheless, how IL-9 and Th/Tc9 cells contribute to the immune responses to cancer remains to be elucidated." (PMID 37835465, 2023). "The studies in cancer patients who underwent nivolumab treatment and preclinical studies allow suggesting that PD-1 blockade induces IL-9 responses in tumors which in turn promote CD8 T cell functions." (PMID 37189417, 2023). "PaTu8988T amoeboid cells were shown to secrete high levels of interleukins [such as interleukin-1α (IL-1α), IL-5, IL-6, IL-7, IL-8, and IL-9], as well as several chemokines involved in cancer progression." (PMID 37851808, 2023). "Different cytokine-related pathways were upregulated in the stroma during the progression from normal mucosa to carcinoma, including interferon γ, interleukin (IL)-11, IL-10, IL-6, IL-9, IL1R and IL-18 signalling pathways." (PMID 36442992, 2023). "Next, we performed a migration assay to test if the IL-9/macrophage axis impacts cancer cell migration." (PMID 35778404, 2022). "Th9 and IL-9 are similarly considered complementary to Th17 cells, and have similarly been found to promote cancer metastasis, potentially in combination with Th17." (PMID 34026764, 2021). "At the same time, factors that are well-recognized as immunosuppressive and cancer growth-inhibiting (i.e., IL-2 and IL-9) were downregulated (<−0.5 log of change)." (PMID 34771587, 2021). "It is noteworthy that additional careful evaluation of IL-9 secretion in both solid and hematologic malignancies is required before considering its potential use as an anti-cancer therapeutic." (PMID 34944921, 2021). "Thanks to IL-6 autocrine and paracrine stimulus, CAFs upregulate VEGF, activate the JAK2/STAT3 pathway, express MCP-1, CCL11/8/20, CXCL5 and IL-9 for cancer cell invasion, growth and survival." (PMID 34944856, 2021). "Recently, IL-9, as a double-edged sword in the development of cancers, has attracted extensive attention." (PMID 32228589, 2020). "Current studies show that Th9 cells play a vital antitumor role in most solid tumors, but IL-9, as a lymphocyte growth factor, can also promote cancer progression in hematological tumors." (PMID 33488574, 2020). "The majority of IL-9-producing cells in cancer are TH9 cells; however, IL-9 can also be secreted by Vδ2+ γδ T cells (the dominant γδT-cell subset), group 2 innate lymphoid cells (ILC2s), and some cytotoxic T cells." (PMID 33329510, 2020). "From a molecular cancer point of view, thrombocytosis has been illustrated to be stimulated by cancer-mediated production of cytokines, most commonly interleukins (IL-1, IL-3, IL-6, and IL-9) and granulocyte-macrophage colony-stimulating factor (GM-CSF)." (PMID 29736362, 2018).
cancer (continued). "Th9 and IL-9 were shown to have direct pro-apoptotic effects on cancer cells and pro-survival effects on T cells." (PMID 29891791, 2018). "Altogether, this suggests that in a cancer setting, TH9 cells are capable of maintaining IL-9- and IL-21-secreting potential, at least long enough to carry out their anti-cancer functions in vivo." (PMID 27832300, 2017). "Kim and colleagues then investigated the role of CD8 T cell responses in the IL-9-dependent anti-cancer efficacy of the DTA-1 treatment." (PMID 27832300, 2017). "Given the multiple function of IL-9, Th9 cells participate in the pathogenesis of a number of diseases, such as cancer, allergic inflammation, and parasitosis." (PMID 28002799, 2017). "The studies analyzing IL-9 are scarce and result from side observations in cancer cell lines." (PMID 40007535, 2025). "Challenges in using IL-9 targeted therapies may arise from its pleiotropic effects on multiple cell types, including Th9, Th17, Tregs, B cells, epithelial and cancer cells." (PMID 41030439, 2025). "In addition, IL-9 can inhibit the TGF-β/Smad pathway, which limits the loss of E-cadherin and reduces cancer cell migration." (PMID 40362280, 2025). "Thus, IL-9 is being explored therapeutically for enhancing its activity in cancer immunotherapy or inhibiting its function in IL-9-responsive malignancies." (PMID 41030439, 2025). "In addition to the standard cytokines, other molecules, such as IL-4, IL-9, and IL-24, are of research interest; they seem to act at different levels of the anti-cancer immune axis." (PMID 40722601, 2025). "Therefore, caution must be exercised when targeting an IL-9-armed OV towards a specific type of cancer." (PMID 38473379, 2024). "First, IL-9 can act as a double-edged sword in cancer development." (PMID 38473379, 2024). "The antitumor effects can be enhanced in combination with an immune checkpoint blockade, indicating a potential translation of the IL-9-expressing oncolytic virus into a clinical trial to enhance the antitumor effects elicited by immune checkpoint blockades for cancer immunotherapy." (PMID 38473379, 2024). "IL-9-producing Tregs have been detected in human non-small cell lung cancer samples, while others have found that IL-9R expression is significantly enhanced in endometrial cancer compared to other cancer types such as renal or breast cancers." (PMID 37455828, 2023). "Because the microbiota controls the response to PD-1 blockade in various human cancers, these results further suggest that IL-9-producing T cells may mediate the effects of the microbiota in response to anti-PD-1 treatment." (PMID 37189417, 2023). "In the context of cancer, IL9 was shown to be a growth factor in most hematologic malignancies." (PMID 36968220, 2023). "Furthermore, there are few studies that directly assessed the expression of IL-5, IL-9, or their receptors in human cancer." (PMID 37455828, 2023). "In macrophage-enriched cancers, IL9 polarizes TAMs to the M1 phenotype and triggers antitumor immunity by inducing chemotactic recruitment and the in situ accumulation of antitumor immune cells, including dendritic cells (DC), macrophages, T cells, and NK cells in CXCL9- and CCL3-dependent manners." (PMID 36968220, 2023). "Recent studies have described the dichotomous function of IL-9 in various cancer diseases." (PMID 33803218, 2021). "This dichotomous function of IL-9 has been described in various cancer diseases." (PMID 33803218, 2021). "In summary, our findings highlight a promising clinical potential of human IL9-secreting T cells for CAR-T cell immunotherapy for human cancers, attributed to their central memory phenotype and that they are less exhausted, hyperproliferative, and long-lived in vivo." (PMID 33214555, 2020). "IL-9-producing T cells can harbour potent anti-cancer functions." (PMID 32624577, 2020). "IL9 yields different responses depending on the cancer type." (PMID 33329510, 2020).
cancer (continued). "Indeed, published studies have explored the role of IL-9 in different types of cancers, and both antitumor and protumor effects have been reported." (PMID 31637216, 2019). "The release of IL-9 has been proposed to account for anti-cancer efficacy." (PMID 31412566, 2019). "In addition to its role in immune and inflammatory diseases, emerging evidence indicates that IL-9 participates in the pathogenesis of cancers, acting mostly as a cancer development promoting factor, especially in nonsolid tumors." (PMID 28349057, 2017). "However, the links between IL-9 and cancer progression have been recently revisited following the discovery of TH9 cells." (PMID 27832300, 2017). "Therefore, we can hypothesize that the role of IL-9 in hampering the anti-tumoral activities of T cells depends on the specific cancer type." (PMID 39281678, 2024). "However, it is found that the classical type 2 immune cytokines IL-4, IL-5, IL-9, and IL-13 may have conflicting roles in cancer." (PMID 37455828, 2023). "Moreover, IL-9 facilitated intercellular adhesion of these cancer cells to pleural mesothelial cell monolayers suggesting that this cytokine may be involved in malignant pleural effusion and pleural metastasis." (PMID 35514957, 2022). "Therefore, according to the literature data, targeting IL-9 and the IL-9 pathway might be a potential strategy and a great promise for treating and fighting cancer." (PMID 33803218, 2021). "However, it is necessary to identify the cellular origin of IL-9, as it is still not determined which cell types are susceptible to its production in most cancer diseases." (PMID 33803218, 2021). "However, the role of IL-9 in cancer including LSCC is not completely understood yet." (PMID 33803218, 2021). "However, Th9 cells-secreting IL-9 yielded different responses depending on types of cancers." (PMID 34177894, 2021). "However, recent studies found that cholesterol or its derivatives, through LXR Sumoylation, can reduce the binding of P65 to the IL-9 promoter and further inhibit the expression of IL-9, thereby inhibiting Tc9 cells differentiation and its anti-cancer response." (PMID 31519198, 2019). "Moreover, contradictory data may also stem from differential effects of IL-9 on immune (antitumor) vs. cancer (protumor) cells." (PMID 31637216, 2019). "Altogether, our data identified new pathway that is essential for the induction of IL-9 in Th9 and Th17, and thus could potentially be used in designing targeted therapies aimed at alleviating the course of IL-9-mediated allergic inflammation and cancer immunotherapy." (PMID 28993609, 2017). "It seems that IL-9 induces cancer cell apoptosis via various pathways; it may depend on cell types." (PMID 28002799, 2017). "IL-9 enhances the activity of CD8+ lymphocytes and M1 macrophages, which inhibit EMT and support the maintenance of the epithelial phenotype of cancer cells." (PMID 40362280, 2025). "Il9−/− mice showed dramatically diminished lung tumor growth when intravenously injected with 4T1, CT26 or TUBO cancer cell lines, indicating a tumorigenic role in the lung environment." (PMID 35778404, 2022). "This study indicates that lipid peroxidation regulates Tc9 cell longevity and antitumor effects via the IL-9/STAT3/fatty acid oxidation pathway and regulating T cell lipid peroxidation can be used to enhance T cell–based immunotherapy in human cancer." (PMID 35192544, 2022). "Based on the Pan-cancer clinical data extracted from the TCGA dataset and TIMER platform, we found that IL9 was up-regulated in various cancer types, including EC." (PMID 33329510, 2020). "IL-9-producing CD4+ helper T cells (Th9 cells) are a subset of CD4+ helper T cells with proinflammatory functions and anti-cancer properties in vivo." (PMID 31412566, 2019). "The Th9 fate is characterized by the secretion of IL-9 by CD4+ T cells, leading to several pro-inflammatory and anti-cancer effects." (PMID 29891791, 2018).
cancer (continued). "In this review, we discuss recent findings that provide strong impetus to revisit the links between IL-9 and cancer progression and highlight the relevance of modulating TH9 cell functions for cancer immunotherapy." (PMID 27832300, 2017). "Activation of GITR by its ligand enhances IL-9 expression in a STAT6- and NF-κB-dependent manner, followed by anti-cancer immune responses." (PMID 27832300, 2017). "As typical examples, b-FGF, IL-9, IP-10, RANTES, and G-CSF were higher in supernatant of CSCs culturing, while TGF-β1, TGF-β3, IL-5, IL-12, and PDGF-BB were higher in supernatant of cancer cells culturing." (PMID 25118635, 2014). "CD8+T-cells are key in cancer defense, maturing into cytotoxic cells through TCR engagement with MHC-II on APCs, supported by co-stimulatory signals (CD28/CD80/CD86) and cytokines like IL-2, IFN-γ, and IL-9 from Th1 and Th9 cells." (PMID 40260236, 2025). "Cancer cells modulate the expression and secretion of several anti-proliferative molecules on DBMSCs, including, CD40LG, CXCL9, IL9R, IL-15, TNFSF13B, IL-9, IL-17, and CXCL1." (PMID 39768220, 2024). "It is noteworthy that beyond IL-9 and IL-21, TH9 cell-derived IL-3 could additionally contribute to the induction of adaptive anti-cancer immune responses." (PMID 27832300, 2017). "Importantly, these anti-cancer properties were found to depend, at least in part, on TH9 cell-derived IL-9." (PMID 27832300, 2017). "The Tc9-specific antitumor action of IL-9 involves self-activation of IL-9 receptors, which, via STAT3 activation, promote lipid peroxidation (LPO) or fatty acid oxidation (FAO) for their energy requirements and escape cancer cell-induced ferroptosis to exert antitumor action." (PMID 41009359, 2025). "Similar to IL-4, currently there are no ongoing clinical trials involving IL-5 or IL-9 in cancer treatment, likely a reflection of our current inadequate understanding of whether they would promote or inhibit cancer under different contexts." (PMID 37455828, 2023). "Interleukin-9 (IL-9) was initially defined as a TH2-type cytokine but was reported to have pleiotropic functions, inducing the proliferation, differentiation, and effector functions of numerous immune cell subsets and plays a critical role in immunity and the pathogenesis of cancers." (PMID 33329510, 2020). "Seven pathways, including the Androgen receptor, Hedgehog, IL-1, IL-5, IL-9, Notch, and Wnt signaling pathways were not significantly perturbed by any condition in our dataset, leaving 13 pathways that were perturbed by at least one cancer." (PMID 22536907, 2012).